MORC2 (MORC family CW-type zinc finger 2)
Diseases named in the same sentence as MORC2 in open-access papers (continued):
Sharing a sentence is not in itself a finding about the gene and the disease.
cancer (continued). "Notably, knockdown of MORC2 promotes mitotic arrest induced by PTX and VCR and enhances the sensitivity of cancer cells to PTX and VCR." (PMID 36967563, 2023). "For example, the acetylation of MORC2 at K67 by NAT10 inhibit histone phosphorylation at H3T11 and induce the transcriptional repression of CDK1 and cyclinB1 to decreases the sensitivity of cancer cell to DNA-damaging chemotherapy and radiotherapy." (PMID 35216622, 2022). "It is worth noting that none of the cancers investigated showed a significant decline in MORC2 expression." (PMID 36234785, 2022). "As an antigen that can be effectively targeted by a specific mAb needs to be expressed on the surface of cancer cells, MORC2 is not an ideal target antigen to develop antibody‐based therapeutics because it is predominantly localized in the nucleus." (PMID 35522895, 2022). "MORC family CW‐type zinc finger 2 (MORC2), a GHKL‐type ATPase, is aberrantly upregulated in multiple types of human tumors with profound effects on cancer aggressiveness, therapeutic resistance, and clinical outcome, thus making it an attractive drug target for anticancer therapy." (PMID 35522895, 2022). "We also got a similar result in MCF-7 cell lines (which has almost no endogenous C/EBPα expression), suggesting that the effect of MORC2 on the proliferation and tumorigenesis of cancer cells is independent of C/EBPα expression." (PMID 30644437, 2019). "Therefore, discovering new drugs targeting MORC2 may enhance the effectiveness of MTAssuch as PTX and VCR against human cancer." (PMID 36967563, 2023). "In multiple cancer cell lines, inhibitors targeting the N-terminal region of heat shock protein 90 (HSP90) destabilize MORC2, while inhibitors targeting the C-terminal region do not." (PMID 39247603, 2024).
tumor (19 papers, 2015 to 2025). "According to the univariate Cox proportional risk model, clinical stage, serum CEA level, tumor T-stage, N-stage, M-stage, clinical treatment effect, radiotherapy, age, and the expression of MORC2 were related to the OS rate of CRC patients." (PMID 39812044, 2025). "While that study focused on MORC2 overexpression and tumor progression, our results emphasize estradiol’s capacity to stabilize Morc2a protein under haploinsufficient conditions." (PMID 40760337, 2025). "It was observed that MORC2 was positively related to clinical stage (P = 0.005), tumor T-stage (P = 0.038), N-stage (P = 0.014), and M-stage (P = 0.023)." (PMID 39812044, 2025). "MORC2 expression was significantly correlated with tumor size (p = 0.018), clinical stage (p = 0.003), lymph node metastasis (pN) (p = 0.010) and distant metastasis (pM) (p = 0.030)." (PMID 39048555, 2024). "Growing evidence has shown that MORC2 not only participates in gene transcription and chromatin remodeling but also plays a key in human disease and tumor development by regulating the expression of downstream oncogenes or tumor suppressors." (PMID 37692502, 2024). "MORC2, an up-regulated protein, plays a crucial role in promoting tumor proliferation and survival by modulating essential signal pathways, thereby contributing to malignant transformation." (PMID 37692502, 2024). "We detected MORC2 expression by IHC and found that high expression of MORC2 in tumor cells in pre-NAC biopsies, not only in univariate analysis but also in multivariate analysis, is significantly associated with a lower pCR rate in TNBC patients." (PMID 37352040, 2023). "The PRD domain of MORC2 interacts with a cadherin-associated protein, catenin delta 1 (CTNND1), to promote tumor invasion and metastasis." (PMID 37892209, 2023). "Conversely, NUDT21 silencing stimulated proliferation and clonogenicity of KIRC cells, and this stimulation was relieved following MORC2 silencing, again supporting that NUDT21 acts as a tumor suppressor in KIRC through downregulating MORC2." (PMID 37737260, 2023). "The relative tumor proliferation capacity was compared by recording the tumor growth curve, which indicated that MORC2 knockdown decreased tumor growth in the HCT-116 xenograft tumor." (PMID 36234785, 2022). "First, MORC2 is aberrantly upregulated in multiple types of tumours and promotes aggressive and therapeutically resistant phenotypes." (PMID 35522895, 2022). "The formation of xenografts tumor with anti-MORC2 and anti-C/EBPα staining in nude mice tissues were verified by immunohistochemical analysis." (PMID 30644437, 2019). "MORC2 exhibited tumor-promoting activities towards CCA cell growth and metastasis by activation of Akt signaling and EMT." (PMID 31180332, 2019). "At 21 days after implantation, tumors harvested from MORC2 knockdown cells exhibited markedly decreased tumor growth rates, average volume and weight." (PMID 31180332, 2019). "Nude mice injected with MORC2-WT or MORC2-SE SGC-7901 cells developed markedly heavier tumor weight and larger volume than vector control and MORC2-SA group." (PMID 25888627, 2015). "This systematic review may provide a favorable theoretical basis for emerging players of MORC2 in tumor development and new insight into the potential clinical application of basic science discoveries in the future." (PMID 37692502, 2024). "In addition to cell proliferation and survival, MORC2 also plays an important role in tumor migration and invasion." (PMID 37692502, 2024). "MORC2 was found to function in KIRC by downregulating tumor suppressor DAPK1 via DNA methylation." (PMID 37737260, 2023). "Furthermore, MORC2 recruits on to the promoters of tumor suppressor genes to repress their transcription and expression to promote oncogenesis." (PMID 37892209, 2023). "Moreover, as demonstrated by the xenograft tumor formation experiment, NUDT21 inhibited tumor formation of Caki-1 cells in vivo, which was reversed by MORC2 recovery." (PMID 37737260, 2023).
tumor (continued). "Moreover, NUDT21 was shown to function as a tumor suppressor in KIRC mainly dependent on MORC2 downregulation." (PMID 37737260, 2023). "Additionally, NUDT21 was confirmed to act as a tumor suppressor mainly depending on downregulation of MORC2." (PMID 37737260, 2023). "In addition, MORC2 is also involved in tumor metabolic reprogramming by regulating glucose metabolism and lipogenesis." (PMID 36234785, 2022). "Thus, we further discovered that MORC2 affects the proliferation of tumor cells by HDAC4 regulating cell senescence." (PMID 36234785, 2022). "MORC2 was significantly over-expressed in 26 of the 33 tumor types, and the expression of MORC2 in CRC tumors was significantly higher than that in peri-cancerous tissues in the paired experimental group (p < 0.001) and the unpaired experimental group (p < 0.001)." (PMID 36234785, 2022). "Functional experiments revealed that the targeting of MORC2 may be an important mechanism by which miR-186-5p exerts its anti-tumor function." (PMID 31180332, 2019). "Knockdown of MORC attenuated tumor cell proliferation, migration and invasion, indicating that MORC2 might act as an oncogene involved in the development of human CCA." (PMID 31180332, 2019). "In addition, MORC2 drove tumor growth by activating Wnt/β-catenin signaling." (PMID 37692502, 2024). "In addition, MORC2 is highly expressed in lung cancer cells and promotes the up-regulation of vascular endothelial growth factor (VEGF) and activation of the Wnt/β-catenin signaling pathway, which triggers the recruitment of tumor-associated macrophages (TAMs) to drive tumor growth." (PMID 37692502, 2024). "circ-DNM3OS induces MORC family CW-type zinc finger 2 (MORC2) expression via sponging miR-145, and inhibition of circ-DNM3OS decreased tumor growth by upregulation of miR-145 and downregulation of MORC2 in xenograft mice." (PMID 34282753, 2021). "NUDT21 functions as a tumor suppressor in KIRC, mainly depending on MORC2 downregulation." (PMID 37737260, 2023). "And the expression levels of MORC2, ELOVL3 and ENO3 were significantly increased in tumor tissues." (PMID 36568396, 2022). "Consistently, tumor tissues exhibited remarkably higher levels of MORC2 protein than those in noncancerous CCA tissues." (PMID 31180332, 2019). "We first performed qRT-PCR to examine the mRNA levels of MORC2 in 44 pairs of CCA specimens (tumor tissue and corresponding nontumorous tissue)." (PMID 31180332, 2019). "Proteomic and biochemical analyses further demonstrated that wild-type MORC2, but not PRD deletion mutant, interacted with catenin delta 1 (CTNND1), a cadherin-associated protein that participates in tumor invasion and metastasis." (PMID 29228664, 2017). "The experiment indicated that depletion of MORC2 significantly reduced the number of metastatic tumours in the lungs in vivo as compared with shNC control, and 17‐AAG more effectively reduced lung metastatic potential in mice bearing shNC tumours than in those injected with shMORC2 cells." (PMID 35522895, 2022). "Furthermore, we found that microRNA (miR)-186-5p, a well-characterized tumor suppressor, can directly bind to the 3′-UTR of MORC2 mRNA, and may function as a scaffold for MORC2, thereby repressing the expression of MORC2 at the post-transcriptional level." (PMID 31180332, 2019). "M276I of MORC2 increased triple-negative breast cancer (TNBC) invasion and metastasis but did not affect cell proliferation or primary tumor growth." (PMID 37692502, 2024). "Additionally, the MORC2 promoter methylation was markedly increased in CRC tissues (P < 0.05), but the methylation of MORC1, MORC3, and MORC4 was significantly lower in the tumor tissues than in negative controls." (PMID 39812044, 2025).
peripheral neuropathy (5 papers, 2021 to 2024). A disorder affecting the peripheral nervous system. "MORC2 heterozygous variants occur in axonal Charcot–Marie–Tooth disease type 2Z, which is characterized by progressive peripheral neuropathy." (PMID 38822427, 2024). "Heterozygous mutations in MORC2 gene have been associated to a spectrum of peripheral neuropathies from the severe early onset DIGFAN syndrome and SMA-like presentation, to the late onset CMT2Z disease." (PMID 35722617, 2022). "MORC2 missense mutation is known to cause peripheral neuropathy of Charcot-Marie-Tooth disease type 2 Z (CMT2Z)." (PMID 34695197, 2021).
infection (3 papers, 2015 to 2021). The state of being infected such as from the introduction of a foreign agent such as serum, vaccine, antigenic substance or organism. "The infection efficiency of lentiviral vectors was about 20%, and about 85% transiently expressed Flag-MORC2 and Flag-MORC2 ΔPRD were localized in the nuclear." (PMID 29228664, 2017).
disease of the peripheral nervous system (1 paper, 2023). "Although CMT is described as a disease of the peripheral nervous system, CNS involvement is reported in the literature in several CMT patients by variations in the MFN2, PMP22, GJB1, GDAP, MORC-2, NDRG1 and NEFL genes." (PMID 37238449, 2023).
mitochondrial disease (1 paper, 2023). "In this article, we present clinical and molecular findings of 219 patients with LS and give the detailed description of three cases with rare findings in nuclear genes MORC2, NARS2 and VPS13D, demonstrating wide genetic heterogeneity of this mitochondrial disease." (PMID 36675121, 2023).
myopathy (1 paper, 2021). A disease of the muscle in which the muscle fibers do not function properly. "Other possible genetically causes of myopathy were ruled out, however, the possibility of a coincidental association between an idiopathic hyperCKaemia and MORC2 mutation cannot be excluded." (PMID 34059105, 2021).
MORC2 also shares sentences with these, for which no sentence is quoted: neurodevelopmental disorder (4 papers); neurological disorders (4); cerebellar ataxia (2); developmental delay, impaired growth, dysmorphic facies, and axonal neuropathy (2); acute myeloid leukemia (1); Bosma arhinia microphthalmia syndrome (1); cerebral malaria (1); cervical cancer (1); chronic myeloid leukemia (1); cognition disorder (1); Hepatic steatosis (1); Macrocephaly (1); microcephaly (1); Motor axonal neuropathy (1); motor neuron degeneration (1); Obesity (1); Onset (1); ovarian carcinoma (1); pancreatic cancer (1); pancreatic ductal adenocarcinoma (1); scoliosis (1); situ carcinoma (1); sterility (1).